LINC00997 (long independently transcribed non-coding RNA 997)
Gene: Long non-coding RNA gene on chromosome 7 (32,760,279 to 32,762,924, forward strand). Ensembl gene ENSG00000281332.
Diseases named in the same sentence as LINC00997 in open-access papers:
LINC00997 is named in the same sentence as 4 diseases in open-access papers, as found by Europe PMC text mining. Sharing a sentence is not in itself a finding about the gene and the disease. The quoted sentences say what the papers report.
colorectal cancer (1 paper, 2022). A primary or metastatic malignant neoplasm that affects the colon or rectum. "Shi’s research suggests that LINC00997 promotes colorectal cancer metastasis by targeting miR-512-3p." (PMID 35846130, 2022).
renal clear cell carcinoma (1 paper, 2022). "In renal clear cell carcinoma, higher levels of LINC00997 are associated with lower OS and disease-free survival." (PMID 35303965, 2022).
tumor (3 papers, 2021 to 2022). "In addition, LINC00997 showed a high correlation with PD-L2; thus, the function of LINC00997 in the tumor immune microenvironment deserves further research." (PMID 36011053, 2022). "Results revealed that LINC00997 was frequently overexpressed in MCRC tissues, which was positively related to the tumor metastasis and stage." (PMID 33570445, 2021).
LINC00997 also shares sentences with these, for which no sentence is quoted: cancer (1 paper).